RNASEL (ribonuclease L)
Diseases named in the same sentence as RNASEL in open-access papers (continued):
Sharing a sentence is not in itself a finding about the gene and the disease.
prostate carcinoma (continued). "Moreover, our analysis suggested that the Asp541Glu polymorphism was associated with increased prostate cancer risk among Europeans and Africans but not among Asians in all genetic models, although Asp541Glu produced similar levels of RNASEL activity to those of the wildtype enzyme." (PMID 23554651, 2010). "Finally, several germline mutations or variants in RNASEL have been observed among hereditary prostate cancer cases, indicating that polymorphic changes within the RNASEL gene may be associated with increased risk of familial but not sporadic prostate cancer." (PMID 19356222, 2009). "To date, germline mutations have been found in three candidate genes for hereditary prostate cancer: ELAC2 at 17p11, RNASEL at 1q25 and MSR1 at 8p22." (PMID 15714208, 2005). "However, RNASEL does not account for a significant number of familial prostate cancers in Germany, and the penetrance of deleterious mutations may need further evaluation." (PMID 15714208, 2005). "In summary, our investigation supports a role for BRCA2 and HOXB13 mutations in prostate cancer predisposition and provides reassurance that BRCA1, RNASEL, and ELAC2 are not substantially contributory in this cohort." (PMID 40433050, 2025). "In summary, several studies provide strong support, both functional and epidemiological, that RNASEL plays a role in prostate cancer, but other studies have suggested a lack of role based on the ethno-geographic origins of study populations." (PMID 35655265, 2022). "A commonly diagnosed cancer, prostate cancer (PrCa), is being regulated by the gene RNASEL previously known as PRCA1 codes for ribonuclease L which is an integral part of interferon regulated system that mediates antiviral and antiproliferative role of the interferons." (PMID 26236721, 2015). "Until now the RNASEL gene has been identified in many studies as the most important hereditary prostate cancer gene although other studies have not supported these findings." (PMID 24282788, 2013). "Xenotropic murine leukemia related virus (XMRV) belongs to the Retroviridae family, Orthoretrovirinae subfamily and Gammaretrovirus genus, which was identified in 2006 while studying the lack of ribonuclease L coding antiviral gene RNASEL function in patients with prostate cancer." (PMID 30285773, 2018). "Although rare variants of other genes such as RNASEL, MSR1, and ELAC2 have been previously identified in prostate cancer families and proposed as prostate cancer susceptibility alleles, follow-up studies have not supported their candidacy." (PMID 23064873, 2013). "For prostate cancer, we analyzed 5 genes and did not observe an over-representation of SNP associations at p<0.05 (observed/tested: BRCA2, 2/83; ELAC2, 1/9, HOXB13, 0/2; MSR1, 1/22; RNASEL, 2/21)." (PMID 23555315, 2013). "Fischer and coworkers studied material from 105 German patients with sporadic prostate cancer and found only one individual positive for XMRV by nested RT-PCR, but this individual did not display the QQ RNaseL genotype." (PMID 19835577, 2009).
breast carcinoma (17 papers, 2008 to 2026). "In total, 3/5 early-onset affected probands carriers of RNASEL:p.Glu265* also harboured a pathogenic mutation in a known breast cancer susceptibility gene." (PMID 29422015, 2018). "Allelic variation of RNaseL may modify the risk of breast cancer in patients carrying high risk mutations." (PMID 35505346, 2022). "Our findings suggest that RNASEL:p.Glu265* could be a genetic modifier of cancer predisposition for carriers of high-risk mutations in different breast cancer susceptibility genes." (PMID 29422015, 2018). "Thus, in probands with early onset disease, the prevalence of RNASEL:p.Glu265* in carriers of a pathogenic mutation in a breast cancer susceptibility gene was 10% (3/30), compared to 0.36% (2/556) in non-carriers (p < 0.002, two-sided Fisher’s Exact test)." (PMID 29422015, 2018). "Our study suggests that RNASEL:p.Glu265* may be a genetic modifier of risk for early-onset breast cancer predisposition in carriers of high-risk mutations." (PMID 29422015, 2018). "Germline mutation in RNASEL (ranked at 15) predicted increased risk of breast cancer." (PMID 21799737, 2011). "However, the mechanisms by which RNASEL could influence the risk of breast cancer are still unknown and should be further investigated." (PMID 29422015, 2018). "Among these, ABCC3, ACPP, PPP1CA, PRKAG3, and RNASEL exhibited interactions with several proteins, immune checkpoint markers, and chemotherapeutic drugs administered in both human breast cancer and FMC." (PMID 40839607, 2025). "Gene-panel testing of BRCA1, BRCA2, PALB2 and RNASEL in the Australian Breast Cancer Family Registry identified five carriers of RNASEL:p.Glu265* in 591 early onset breast cancer cases." (PMID 29422015, 2018). "RNASEL, an enzyme central to interferon-related antiviral and apoptotic responses, has been linked to increased risk for CESC, head and neck squamous cell carcinomas, and breast cancer through single nucleotide polymorphisms such as rs3738579." (PMID 37735483, 2023). "When MT was expressed in human breast cancer cells we found that the interferon response depended on the presence of RNaseL and interferon regulatory factor 7 (IRF7), the key effector molecules at the proximal and distal ends of the OAS-RNaseL signaling pathway." (PMID 35505346, 2022). "Our study did not provide any evidence for a modifying role for RNASEL:p.Arg462Gln in breast cancer predisposition." (PMID 29422015, 2018). "Three of the five women (60%) carrying RNASEL:p.Glu265* also carried a pathogenic mutation in a breast cancer susceptibility gene compared with 30 carriers of pathogenic mutations in the 586 non-carriers of RNASEL:p.Glu265* (5%) (p < 0.002)." (PMID 29422015, 2018). "Recent reports suggest that not only RNase L is a marker for HPC but also germline mutations in RNASEL may predict an increased risk of head neck, uterine, cervix, and breast carcinoma." (PMID 25254215, 2014). "However, the role of RNASEL in human breast cancer remains controversial." (PMID 40839607, 2025). "Therefore, further investigation into the role of RNASEL in mammary tumors is warranted." (PMID 40839607, 2025). "We found that ABCC3, ACPP, PPP1CA, PRKAG3, and RNASEL were involved in the tumorigenesis of FMC and exhibited interactions with proteins and chemotherapeutic drugs relevant to both human breast cancer and FMC." (PMID 40839607, 2025). "However, our data indicate that in women with early-onset disease (diagnosed under 40 years old) the frequency of carriers of pathogenic mutations in a breast cancer susceptibility gene was significantly higher in RNASEL:p.Glu265* carriers than in RNASEL:p.Glu265* non-carriers." (PMID 29422015, 2018). "RNASEL plays a significant role in viral clearance and it has been suggested that variation in RNASEL may alter risk of viral-associated cancers, such as head and neck squamous cell carcinoma and cervical cancer, as well as non-viral cancers such as breast cancer." (PMID 24699816, 2014).
lung carcinoma (11 papers, 2014 to 2025). "In this study group, one of the two females that presented the RNASEL gene variant was affected by early onset BC, showed a case of hepatocarcinoma (her father) and lung cancer too (her paternal cousin) among her family members (P13)." (PMID 36035419, 2022).
COVID-19 (8 papers, 2021 to 2025). A disease caused by infection with severe acute respiratory syndrome coronavirus 2. "This study aimed to analyze the frequency of three gene variants of OAS and RNASEL with the occurrence of COVID-19 symptoms and disease outcome." (PMID 38673053, 2024). "In this study, we examined the frequency of three gene variants within the OAS family (OAS1, OAS2, and OAS3) and one in RNASEL, in relation to the manifestation of COVID-19 symptoms and the overall disease prognosis." (PMID 38673053, 2024). "Vaccines against COVID-19 should not activate the RNaseL cascade and therefore should not increase the incidence of T1D." (PMID 36307540, 2022).
HIV-1 infection (6 papers, 2009 to 2024). The type species of lentivirus and the etiologic agent of acquired immunodeficiency syndrome (AIDS). "An induction of RNaseL during HIV-1 infection and downregulation of the 2-5A/RNaseL pathway has been described in human T cells." (PMID 37209263, 2023). "We next investigated whether RNaseL levels could be influenced by HIV-1 infection or by changes in ocln expression levels." (PMID 37209263, 2023). "Thus, HIV-1 infection of human pericytes does not appear to involve RNaseL as an antiviral mechanism." (PMID 37209263, 2023). "No changes were found in the expression of RNaseL at mRNA or protein levels after HIV-1 infection." (PMID 37209263, 2023). "Interestingly no changes were found in RNaseL after HIV-1 infection." (PMID 36778388, 2023).
familial prostate cancer (5 papers, 2007 to 2017). Prostate carcinoma that has developed in relatives of patients with a history of prostate carcinoma. "In particular, a combined positional cloning and candidate gene approach identified the RNase L gene (RNASEL) as a candidate for the hereditary prostate cancer 1 (HPC1) locus at human chromosome 1q24–25." (PMID 26517238, 2015).
Rotavirus infection (5 papers, 2017 to 2022). Infection with any of the rotaviruses. "It was reported that the OAS/RNaseL pathway is activated during rotavirus infection and is important for the defense of IECs." (PMID 34163470, 2021). "Rotavirus infection increased the expression of IFN-β and IFN-λ3 as well as the antiviral factors PKR, Mx1, and RNAseL in PIE cells." (PMID 34163470, 2021).
cervical carcinoma (4 papers, 2008 to 2018). A carcinoma arising from either the exocervical squamous epithelium or the endocervical glandular epithelium. "Furthermore, the reported link between XMRV expression and RNASEL variant R462Q suggests that XMRV expression should be looked for in cervical smears, as germline mutations in RNASEL have also been shown to predict an increased risk of cervical cancer." (PMID 23056612, 2012).
melanoma (4 papers, 2011 to 2022). A malignant, usually aggressive tumor composed of atypical, neoplastic melanocytes. "We had previously shown that polymorphisms of RNASEL and miR-146a genes were associated with melanoma in a sex-specific manner." (PMID 36286041, 2022). "Dissimilar results were obtained with miR-146a mimic transfection in A375 melanoma cells after treatment with each hormone, in which RNASEL transcript level was slightly upregulated." (PMID 36286041, 2022). "Polymorphisms in the ribonuclease L (RNASEL) coding gene and hsa-miR-146a-5p (miR-146a) have been associated with melanoma in a sex-specific manner." (PMID 36286041, 2022). "Our results indicate that RNASEL is a direct target of miR-146a in both melanoma cell lines." (PMID 36286041, 2022). "In the present work, firstly we assessed whether RNASEL mRNA could be a direct target of miR-146a in LM-20 and A375 melanoma cells and in HaCaT cells." (PMID 36286041, 2022). "In conclusion, the results obtained in this study suggest that sex hormones may act on miR-146a, on RNASEL gene expression, and especially on RNase-L protein level with a view to contribute to the female advantages observed in melanoma incidence and survival." (PMID 36286041, 2022). "Finally, we measured the endogenous levels of miR-146a and RNASEL/RNase-L expression in melanoma cells treated with either testosterone or 17β-estradiol." (PMID 36286041, 2022). "Ribonuclease L has been reported to interact with microRNA-146a as a sex-specific factor in melanoma, and semaphorin 7A has been found to reduce the pulmonary metastasis of melanoma." (PMID 33193373, 2020). "Melanoma cells were incubated with testosterone or 17β-estradiol for 24 h and subsequently the expression levels of miR-146a, RNASEL and RNase-L were evaluated by qPCR or Western Blot analyses." (PMID 36286041, 2022). "The present work intended to investigate, in sex-hormone-treated melanoma cell lines, the contribution of RNASEL, its product RNase-L enzyme, and miR-146a in the female advantages observed in melanoma incidence and survival." (PMID 36286041, 2022). "Subsequently, we investigated in the context of melanoma cells whether testosterone or 17β-estradiol administration may affect the endogenous expression of RNASEL and miR-146a genes and RNase-L protein." (PMID 36286041, 2022). "At the present point, we attest that RNASEL mRNA is a target of miR-146a since the binding of miR-146a to RNASEL 3′UTR region lowers the luciferase reporter activity in two melanoma cell lines and non-transformed keratinocytes, as well." (PMID 36286041, 2022). "Moreover, overexpression of miR-146a by mimic transfection in the presence of either testosterone or 17β-estradiol can decrease RNase-L protein expression without interfering with RNASEL mRNA level in LM-20 melanoma cells." (PMID 36286041, 2022).
autoimmune disease (3 papers, 2024). A disorder resulting from loss of function or tissue destruction of an organ or multiple organs, arising from humoral or cellular immune responses of the individual to their own tissue constituents. "RNASEL is involved in intracellular single RNA cleavage as part of the dsRNA detection system and antiviral response, but the dysfunction of RNASEL also increases the risk of cancer and autoimmune disease in an apparently autosomal dominant manner." (PMID 39062917, 2024).
lung adenocarcinoma (3 papers, 2017 to 2019). A carcinoma that arises from the lung and is characterized by the presence of malignant glandular epithelial cells. "We show that the cell-lethal phenotype of ADAR1 deletion in human lung adenocarcinoma A549 cells is rescued by CRISPR/Cas9 mutagenesis of the RNASEL gene or by expression of the RNase L antagonist, murine coronavirus NS2 accessory protein." (PMID 28362255, 2017).
Obesity (3 papers, 2016 to 2025). Accumulation of substantial excess body fat. "Top genes differentially methylated between these cohorts included the obesity-protective MFAP2 gene as well as cancer risk susceptibility genes APOL3 and RNASEL." (PMID 39844333, 2025).
pancreatic cancer (3 papers, 2014 to 2021). "The RNASEL germline variants were associated with not only familial PCa, but also pancreatic cancer, which indicated the potential mechanisms between pancreatic cancer and PCa development." (PMID 29784056, 2018).
prostate tumor (3 papers, 2007 to 2017). "A novel gammaretrovirus named xenotropic murine leukemia virus-related virus (XMRV) has been recently identified and found to have a prevalence of 40% in prostate tumor samples from American patients carrying a homozygous R462Q mutation in the RNaseL gene." (PMID 19835577, 2009). "Germline and sporadic mutations of RNAseL are found in the majority of prostatic tumors, including LNCaP cells, and result in a reduced enzymatic activity and capacity of cells to respond to the activation of interferons, likely favoring the development of prostate tumors." (PMID 17925854, 2007).
Aicardi-Goutières syndrome (2 papers, 2022 to 2025). "For example, the overactivation of RNASEL may contribute to neurodevelopmental and inflammatory genetic disorders such as Aicardi–Goutières syndrome." (PMID 36424644, 2022).
leukemia (2 papers, 2022 to 2024). A malignant (clonal) hematologic disorder, involving hematopoietic stem cells and characterized by the presence of primitive or atypical myeloid or lymphoid cells in the bone marrow and the blood. "CR + LSD1 inhibition leads to the re-activation of dsRNA/IFN signaling, massive RNASEL-dependent apoptosis, and complete leukemia eradication in ~90% of mice." (PMID 38280853, 2024).
neuroblastoma (2 papers, 2019 to 2020). Neuroblastoma (NB) is the most common solid, extracranial childhood tumor. "For example, IFN-β treatment led to death of neuroblastoma cells through activation of the OAS/RNAseL system, activation of PKR, and differential regulation of STATs as well as inhibition of pro-survival signaling by the PI3k/AKT pathway." (PMID 32106552, 2020).
sarcoma (2 papers, 2021 to 2022). A usually aggressive malignant neoplasm of the soft tissue or bone. "Upregulated mtRBP genes included Fus (fused in sarcoma), Puf (pumillo and FBF 60 homolog), Rexo2 (RNA exonuclease 2), and RNasel and RNase4 (ribonucleases)." (PMID 35754828, 2022).
ampulla of vater cancer (1 paper, 2012). A primary or metastatic malignant neoplasm involving the ampulla of Vater. "We also found an increased risk of ampulla of Vater cancer with RNASEL rs672527, which is located in an intronic region of the gene." (PMID 23057767, 2012). "Suggestive associations were observed for SNPs in VEGFA with biliary stones, IL8 with gallbladder and ampulla of Vater cancers, and RNASEL with ampulla of Vater cancer (false discovery rate≤0.2)." (PMID 23057767, 2012).
biliary tract cancer (1 paper, 2012). "Data from our population-based study of biliary tract cancers in Shanghai suggested that variants in PTGS2, IL8, IL8RB, RNASEL, NOS2 and VEGF were associated with biliary tract cancer and/or stones." (PMID 23057767, 2012).
depression (1 paper, 2024). "Multiple identified genes, such as RNASEL, RGS16, RFX4 and ROBO2 were reported to be associated with chronotype, depression or cognition in previous studies." (PMID 38778419, 2024). "GWAS detected 15 loci significantly associated with chronotype in the subjects with self-reported depression, such as rs12736689 at RNASEL (P = 1.00 × 10− 09), rs509476 at RGS16 (P = 1.58 × 10− 09) and rs1006751 at RFX4 (P = 1.54 × 10− 08)." (PMID 38778419, 2024). "Thus, RFX4, RGS16, RNASEL and ROBO2 may be the important genetic factors indirectly linked to sleep disturbances and depression via circadian rhythm or neurotransmitters." (PMID 38778419, 2024). "Moreover, study supported the association between RGS16/RNASEL and neuroticism, although they are not directly related to depression." (PMID 38778419, 2024).
hereditary non-polyposis colorectal cancer (1 paper, 2018).
liver disease (1 paper, 2017). "Similarly, the efficiency of OAS/RNaseL pathway might result notably altered by the herein identified genetic variants and could be determinant for the progression of the liver disease." (PMID 28704535, 2017).
non-melanoma skin carcinoma (1 paper, 2014). "Main effects of RNASEL rs486907 and MIR146A rs2910164 genotypes on non-melanoma skin cancer risk stratified by sex." (PMID 24699816, 2014). "Main effects of RNASEL rs486907 and MIR146A rs2910164 genotypes on non-melanoma skin cancer risk." (PMID 24699816, 2014). "Gene-gene interaction of RNASEL and MIR146A in relation to non-melanoma skin cancer risk." (PMID 24699816, 2014).
pulmonary tuberculosis (1 paper, 2025). A bacterial infection that affects the lungs and is caused by Mycobacterium tuberculosis. "Our analysis of clinical samples from tuberculosis patients revealed a significant increase in RNASEL expression in the serum of patients with pulmonary tuberculosis compared to healthy volunteers." (PMID 40182927, 2025).
skin cancer (1 paper, 2014). "In this study, a decrease in risk of skin cancer was observed only when both variants, rs486907 RNASEL and MIR146A rs2910164, were present." (PMID 24699816, 2014).
squamous cell carcinoma (1 paper, 2014). A carcinoma arising from squamous epithelial cells. "Using a large population-based case-control study of basal cell (BCC) and squamous cell carcinoma (SCC), we investigated the impact of MIR146A SNP rs2910164 on cancer risk, and interaction with a SNP in one of its putative targets (RNASEL, rs486907)." (PMID 24699816, 2014).